PODXL (podocalyxin like)
Diseases named in the same sentence as PODXL in open-access papers (continued):
Sharing a sentence is not in itself a finding about the gene and the disease.
colon carcinoma (12 papers, 2014 to 2024). "Although the clinical significance of PODXL expression in colon cancer has been reported, the underlying molecular mechanism is still unclear." (PMID 28946619, 2017). "Results showed that expression of PODXL was significantly associated with the YAP signature in four public colon cancer datasets." (PMID 28946619, 2017). "Moreover, colon cancer patients overexpressing PODXL were confirmed to be associated with poor survival outcomes." (PMID 28946619, 2017). "TAZ is the key transducer of Hippo signalling and a novel downstream signalling transducer of PODXL in mediating cancer invasiveness and stemness properties in colon cancer." (PMID 38468490, 2024). "PODXL expressed on LS174T colon cancer cells and various pancreatic carcinomas binds to both E- and L-selectins with high affinity." (PMID 34201212, 2021). "Inhibition of PODXL in HCT15 colon cancer cells results in a downregulation of TAZ and its downstream targets, leading to a suppression of tumour invasion." (PMID 34201212, 2021). "Colon cancer cells HT29 and HCT15, two cell lines that highly express PODXL, are resistant to the widely used colon cancer chemotherapy drugs 5-fluorouracil and irinotecan." (PMID 34201212, 2021). "In colon cancer, coexpression of the PDZ-binding motif (TAZ) with PODXL is associated with poor survival outcomes." (PMID 34201212, 2021). "Together, these data indicate that PODXL plays an important role in drug resistance, and that developing therapeutic tools against PODXL is urgently needed for treating colon cancer." (PMID 28946619, 2017). "Our study shows consistent results that expression of PODXL is associated with EMT genes in colon cancer patients, and, conversely, suppression of PODXL-downregulated EMT genes in colon cancer cells." (PMID 28946619, 2017). "Our findings demonstrate the potentiality of PODXL as a biomarker and therapeutic target for colon cancer." (PMID 28946619, 2017). "In this study, we revealed that TAZ is a novel downstream signaling transducer of PODXL in mediating cancer invasiveness and stemness properties in colon cancer." (PMID 28946619, 2017). "To further validate the feasibility of inhibiting PODXL or TAZ for colon cancer treatment, we examined the effect of the TAZ inhibitor, verteporfin (VP), on colon cancer HCT15 cells." (PMID 28946619, 2017). "In the present study, we revealed that the Hippo transducer, the transcriptional coactivator with PDZ-binding motif (TAZ), acts as a downstream mediator of PODXL in colon cancer." (PMID 28946619, 2017). "In addition, PODXL serves a critical role in cancer stemness, invasiveness and conferred chemotherapy resistance in HT29 and HCT15 colon cancer cells that expressed high PODXL levels." (PMID 31083655, 2019). "Moreover, PODXL plays a critical role in cancer stemness, invasiveness, and sensitivity to chemotherapies in colon cancer HCT15 cells." (PMID 28946619, 2017). "Interestingly, we found HT29 and HCT15 colon cancer cells that expressed high level of PODXL were more resistant to 5-flurouracil (5-FU) and irinotecan (CPT11), two conventional chemotherapies widely used for colon cancer treatment." (PMID 28946619, 2017). "Moreover, the GSEA revealed that expressions of PODXL and TAZ were significantly associated with the stem cell gene signature in colon cancer patients." (PMID 28946619, 2017). "Results of the real-time PCR showed that inhibition of PODXL-downregulated TAZ downstream targets including AXL, CTGF, CYR61, Survivin, and CyclinD1, confirming the association between PODXL and the TAZ signature in colon cancer patients." (PMID 28946619, 2017). "Importantly, inhibition of PODXL significantly reduced the tumorsphere-forming capacity in HCT15 cells, indicating that expression of PODXL is crucial for the self-renewal property of colon cancer cells." (PMID 28946619, 2017).
colon carcinoma (continued). "Moreover, the analysis of mRNA expression levels in patients with colon cancer using GSE17536 datasets revealed a positive correlation of PODXL expression with the mesenchymal markers vimentin, N-cadherin, TWIST2, SLUG, and ZEB1 and a negative correlation with the epithelial marker E-cadherin." (PMID 32046309, 2020). "Notably, expression of PODXL showed a positive correlation with stem-like and epithelial-mesenchymal transition (EMT) core signatures, and was associated with poor survival outcomes in patients with colon cancer." (PMID 28946619, 2017). "Therapy which targets either PODXL or TAZ may have the potential to treat colon cancer." (PMID 28946619, 2017). "For colon cancer, identified biomarkers are CD15, CD104, CD324, CD326, CD49f, and for renal cancer, CD24, CD26, CD106 (VCAM1), EGFR, SSEA-3 (B3GALT5), SSEA-4 (TMCC1), TIM1 (HAVCR1), and TRA-1-60R (PODXL)." (PMID 36221114, 2022). "Ultimately, based on our MCIA, we identified CD15, CD104 (Integrin-β4), CD324 (E-cadherin), CD326 (EpCAM), and CD49f as biomarkers for colon cancer and CD24, CD26 (DPP4), CD106 (VCAM1), TIM-1, SSEA-3 (B3GALT5), SSEA-4 (TMCC1), TRA-1-60-R (PODXL) and EGFR for renal cancer." (PMID 36221114, 2022). "Notably, expression of PODXL exerted a positive correlation with stem-like and EMT core signatures, and contributed to unfavorable prognosis in patients with colon cancer." (PMID 31083655, 2019). "Moreover, coexpression of PODXL and TAZ renders the worst survival rate in colon cancer patients." (PMID 28946619, 2017). "Furthermore, coexpression of PODXL and TAZ in colon cancer patients rendered the worst prognosis." (PMID 28946619, 2017). "However, the mechanistic basis underlying these observations warrants further studies, not least since in vitro data on cell lines from colon cancer, osteosarcoma, oral tongue squamous cell carcinoma and astrocytoma, have demonstrated links between PODXL and resistance to chemotherapy." (PMID 30355278, 2018).
ovarian carcinoma (11 papers, 2012 to 2024). A malignant neoplasm originating from the surface ovarian epithelium. "A recent study demonstrated that forced PODXL expression in ovarian cancer cells decreased their adhesivity by altering β1-integrin levels, and that PODXL expression on the cell surface was associated with poor prognosis in high grade serous carcinomas." (PMID 22769594, 2012). "However, PODXL is overexpressed in several epithelial cancers including pancreatic, breast and ovarian cancer; and importantly this overexpression has been associated with poor prognosis." (PMID 38553472, 2024). "We first examined PODXL expression in HGSC patient tissues (n = 17) by immunohistochemistry, then scrutinized 37 ovarian cancer cell lines for their PODXL expression and analysed the association between the levels of PODXL and the likelihood of being categorised as HGSC." (PMID 38553472, 2024). "While PODXL is detected in normal tissues of the kidney, breast, liver, pancreas, and endometrium, overexpression of PODXL has been associated with poor prognosis and outcomes of several epithelial cancers, including breast and ovarian carcinomas." (PMID 34201212, 2021). "Here, we demonstrated that PODXL is expressed on the surface of both established ovarian cancer cell lines and patient ascites-derived spheroids, and that PODXL levels positively correlated with spheroid compactness." (PMID 38553472, 2024). "We first showed that PODXL was expressed variably in HGSC patient tissues (n = 17) as well as in ovarian cancer cell lines (n = 28) that are more likely categorised as HGSC." (PMID 38553472, 2024). "For ovarian cancer, PODXL is more highly expressed in HGSC (87%) compared to other subtypes, and PODXL cell surface localisation is reported to be significantly associated with poorer disease-free survival." (PMID 38553472, 2024). "PODXL was also expressed by most ovarian cancer cell lines examined (n = 28), and those with high PODXL expression are more likely categorised as HGSC." (PMID 38553472, 2024). "We first searched the EMBL-EBI RNA-seq database and identified 28 ovarian cancer cell lines with PODXL mRNA data available." (PMID 38553472, 2024). "A previous report indicated that PODXL repressed surface levels of β1-integrin in ovarian cancer cells." (PMID 36735782, 2023). "BBOX1-AS1 is a critical player in ovarian cancer, where it upregulates PODXL by sponging miR-361-3p, thereby promoting cancer progression." (PMID 37735639, 2023). "We next examined how PODXL is expressed in ovarian cancer cell lines." (PMID 38553472, 2024). "For instance, BBOX1-AS1 is highly expressed in ovarian cancer, where BBOX1-AS1 augments PODXL by sequestering miR-361-3p to promote cancer progression." (PMID 35188872, 2022).
astrocytoma (7 papers, 2013 to 2023). "In both astrocytoma and osteosarcoma, PODXL expression is associated with resistance to commonly used chemotherapy agents temozolomide and cisplatin, respectively, via a PI3K-dependent pathway." (PMID 34201212, 2021). "In astrocytomas, high expression of PODXL is associated with unfavorable prognosis." (PMID 31083655, 2019). "We examined several astrocytoma cell lines and found that while PODXL was amply expressed in U-87 cells, it was expressed at a low level in SW1783 cells." (PMID 23596468, 2013). "Since tumor cell survival is critical for metastasis, we next examined the effect of PODXL on astrocytoma cell survival against apoptotic stress." (PMID 23596468, 2013). "In the present study, the effect of PODXL on astrocytoma cell invasion and survival against a chemotherapy agent was investigated." (PMID 23596468, 2013). "SW1783 (grade III astrocytoma) cells had a relatively low constitutive expression of PODXL compared with U-87 (grade IV astrocytoma; gliobalstoma) cells." (PMID 23596468, 2013). "In conclusion, we demonstrated that PODXL promotes astrocytoma cell invasion, potentially through upregulating MMP-9 expression in a PI3K-dependent manner." (PMID 23596468, 2013). "We next examined the relationship of PODXL expression with astrocytoma grade on a total of 64 freshly resected gliomas." (PMID 24146797, 2013). "To investigate the effect of PODXL on astrocytoma cell invasion, we performed in vitro cell invasion assays and examined the MMP-9 expression level in the two cell lines." (PMID 23596468, 2013). "LY treatment further increased the apoptosis in the PODXL-knocked down cells.These results suggest that PODXL promotes astrocytoma cell survival against temozolamide in a PI3K-dependent manner." (PMID 23596468, 2013). "As tumor cell survival is critical for metastasis, the effect of PODXL was examined on astrocytoma cell viability against apoptotic stress." (PMID 24179530, 2013). "In conclusion, in the present study it was demonstrated that PODXL promotes astrocytoma cell invasion, potentially through the upregulation of MMP-9 expression in a PI3K-dependent manner." (PMID 23596468, 2013). "Additionally, PODXL was shown to promote astrocytoma cell survival against temozolomide-induced apoptotic stress by enhancing the activation of the PI3K/Akt survival signaling pathway." (PMID 23596468, 2013). "Thus, to investigate the functional role of PODXL in astrocytoma cells, we stably transfected SW1783 cells with PODXL expression vector to overexpress PODXL, and stably transduced U-87 cells with PODXL-shRNA to knock down PODXL." (PMID 23596468, 2013). "This study provides novel insights into the molecular mechanisms underlying astrocytoma progression, cell survival and chemoresistance, and suggests that PODXL may be a potential target for overcoming chemoresistance in astrocytomas." (PMID 23596468, 2013). "However, the role of PODXL in astrocytoma progression remains to be fully elucidated." (PMID 23596468, 2013). "However, it still remains unclear whether PODXL knockdown would impact astrocytoma cell survival against other types of chemotherapy agents." (PMID 23596468, 2013). "Overexpression and knockdown of PODXL were respectively performed in SW1783 (grade III astrocytoma) and U-87 (grade IV astrocytoma; gliobalstoma) cells." (PMID 23596468, 2013). "Taken together, these findings suggest that PODXL enhances the activation of the PI3K/Akt signaling pathway and, thereby, promotes astrocytoma cell survival against apoptotic stress." (PMID 23596468, 2013).
astrocytoma (continued). "PODXL in promoting cancer cell proliferation and survival against chemotherapy and immunotherapy drugs has also be shown in nonepithelial cancers, such as astrocytoma, osteosarcoma, and mature B-cell lymphoma cells." (PMID 34201212, 2021). "PODXL overexpression and knockdown with or without LY treatment did not significantly alter the apoptosis rate of astrocytoma cells in normal culture conditions." (PMID 23596468, 2013). "Since PODXL showed a protective effect on astrocytoma cells against temozolomide-induced apoptotic stress in a PI3K-dependent manner, we investigated the effect of PODXL on the PI3K/Akt survival signaling pathway in astrocytoma cells." (PMID 23596468, 2013). "Additionally, our findings that the selective PI3K inhibitor LY eradicated the effect of PODXL overexpression and extended the effect of PODXL knockdown, suggest that PODXL promotes invasion and MMP-9 expression in astrocytoma cells by a PI3K-dependent mechanism." (PMID 23596468, 2013).
prostate carcinoma (7 papers, 2013 to 2023). A carcinoma that arises from epithelial cells of the prostate gland. "We identified breast and prostate cancer cell lines with high PODXL expression, as PODXL has been associated with invasion and metastasis in these cancers." (PMID 36735782, 2023). "Mutations affecting the extracellular domain of PODXL are associated with an increased risk of prostate cancer and development of a more aggressive prostate cancer." (PMID 24146797, 2013). "This may explain how allelic imbalances and genetic mutations around PODXL may increase the risk of prostate cancer and tumour aggressiveness." (PMID 34201212, 2021). "A locus on the human chromosome 7q32-33 where the PODXL gene is located exhibits a high frequency of allelic imbalance in prostate tumours, where several missense mutations and in-frame deletions within PODXL are associated with increased risk for developing more aggressive prostate cancer." (PMID 34201212, 2021). "In prostate cancer cells, at least, we identify that at the surface, the major function of PODXL resides in its extracellular domain, acting as a rheostat on the integrin-repressing activity of the glycocalyx component GAL3." (PMID 36735782, 2023). "Enforced PODXL expression in breast and prostate cancer cell lines promoted the migrated and invasive abilities by increasing expression of MMP-1 and MMP-9, and activating MAPK and PI3K signaling." (PMID 29748877, 2019). "The association between the CNA expression level of PODXL, the gene encoding TRA, and progression-free survival (PFS) was assessed using the Kaplan-Meier (KM) curve and log-rank test using TCGA PanCancer primary prostate cancer data." (PMID 37153742, 2023). "PODXL mutation rather than overexpression is strongly linked to aggressive prostate cancer." (PMID 34201212, 2021). "This hypothesis is further supported by the previously demonstrated ability of PODXL to form complex with ezrin in breast and prostate cancer cells in vitro, thereby inducing phosphorylation of ezrin and changes in its subcellular location, in turn leading to an increased migration and invasion." (PMID 24885195, 2014). "Our findings revealed, contrastingly and in prostate cancer at least, that GAL3 is an inhibitor of integrin-dependent invasion with PODXL acting as a decoy to release GAL3-mediated repression of integrins." (PMID 36735782, 2023). "PODXL also reportedly leads to increased in vitro migration and invasion, increased matrix metalloproteinase (MMP) expression, and increased activation of phosphatidylinositol 3-kinase (PI3K) in breast and prostate cancer cells." (PMID 23596468, 2013). "We identify an unexpected function of PODXL as a decoy receptor that relieves the invasion-inhibiting effect of the glycocalyx component galectin-3 (GAL3) and demonstrate that the levels of this switch identify prostate cancer patients with high metastasis and poor outcome." (PMID 36735782, 2023).